CD7 (CD7 molecule)
Diseases named in the same sentence as CD7 in open-access papers (continued):
Sharing a sentence is not in itself a finding about the gene and the disease.
leukemia (continued). "CD5 and CD7 expression on the surface of CD45+ cells in the peripheral blood of mice were measured using flow cytometry to assess the effect of CAR-T treatment on heterogeneous leukemia cells." (PMID 35332132, 2022). "All mice treated with CD5 CAR-T and CD5CD7KO T cells progressed steadily, while CD7 CAR-T cells were able to temporarily inhibit neoplastic cells but failed to control the progression of leukemia due to the loss of CD7 antigen on tumor cells." (PMID 35332132, 2022). "In 22/24 recipients injected with hCD45+ G+C+ cells (FACS sorted from day 24–25 N+ LTB-transduced CB cultures), we obtained G+C+ leukemias of T-cell lineage, typically CD7+ CD2+ sCD3+/− CD1a+/− and variable CD4/CD8 pattern including CD4− CD8− (DN), CD4+ CD8+ (DP), and CD4− CD8dim (SP8dim)." (PMID 31266935, 2019). "Interestingly only xenografts from CD7+/CD34+ sorted T-ALL4 leukemic cells were able to initiate leukemia in secondary transplants in accordance with our previous results and secondary T-ALL were 100% IKZF1del positive cells." (PMID 27191650, 2016). "The resulting human leukemia may arise through genetic selection and we previously showed that human T-ALL development in immune-deficient mice is significantly enhanced upon CD7+/CD34+ leukemic cell transplantations." (PMID 27191650, 2016). "As leukemia development relies on clonal selection in xenograft, we hypothesized that the difference in aggressiveness between CD7+/CD34+ and CD7+/CD34− cells relates on the presence in both sub-fractions of distinct genetic subclones." (PMID 27191650, 2016). "As for T-ALL1-3, CD34+ cells produced leukemia in xenograft faster meaning they were more aggressive than CD34− cells although increasing the injected cell number allowed to observe and quantify leukemia development also in CD7+/CD34− cells of all 3 slow-growing T-ALL." (PMID 27191650, 2016). "Besides CD7+/CD34+/− cell fractions from studied T-ALL samples with delayed leukemia development activity are either genetically heterogeneous or homogenous." (PMID 27191650, 2016). "Kinetic analysis of CD7+/CD34+/− leukemic cell growth in vivo using immunohistochemistry did not allow early cell infiltration analysis but revealed higher late infiltration level for CD7+/CD34+-derived xenografts compared to CD7+/CD34−-derived leukemia in accordance with flow cytometry datas." (PMID 27191650, 2016). "The presence of anomalous expression of CD7 in CD34+ cells was more frequent in high-risk MDS and might reflect progression to leukemia." (PMID 25924846, 2015). "Indeed, during in vitro treatment as described here, CD7-negative malignant blasts survived and, in a phase I clinical trial, two of eight AML patients relapsed with CD7-negative leukemia after initially achieving a complete remission with CD7 CAR T cell therapy." (PMID 40589566, 2025). "Therefore, novel anti-CD7 variable fragments may provide us a new option to improve the immunotoxin efficacy on T-cell lymphomas and leukemias." (PMID 27083001, 2016). "Overall, our work reveals that T-ALL cell subpopulations isolated based on cell surface markers, such as here CD34 and CD7 expression, and bearing differential leukemia initiating activity may contain distinct clones, with genetic and probably also, but yet not depicted, epigenetic differences." (PMID 27191650, 2016). "In CD7+/CD34+-derived leukemia, the proportion of IKZF1del positive cells raised to 100% in virtually all (5+/6 mice, 2 experiments) mice, indicating the reproducible selection of the IKZF1del clone, while it was barely detectable in CD7+/CD34−-derived xenografts (0.01% in 2/4 mice, 2 experiments)." (PMID 27191650, 2016). "Further, K12 CAR-T cells selectively eliminated CD7-positive T-ALL cell lines and primary leukemia blasts in vitro and had prominent tumoricidal activity in mice, with three out of five mice having no detectable disease." (PMID 40589566, 2025).
leukemia (continued). "By applying this technique to T cells from a healthy donor, they successfully generated CD7 CAR-T cells (BE-CAR7), achieving initial success in treating three pediatric patients with relapsed leukemia." (PMID 38915099, 2024). "Cells with lymphoid markers were also present in the transcriptionally defined leukemia cells, but in smaller proportions, including CD19+/CD22+/CD30+ cells (5.96%) CD19+/CD22+/CD45+ cells (5.49%), CD3+/CD5+/CD7+ cells (4.45%), and CD3+/CD4+/CD5+ cells (0.4%)." (PMID 39294124, 2024). "They observed that these CD7 CAR-T cells prevented self-destruction and exhibited potent cytolytic activity, significantly halting leukemia progression and extending mouse survival." (PMID 38915099, 2024). "After the third cycle of myeloid-directed therapy, an interesting immunophenotypic shift was observed in which her leukemia cells exhibited increased CD19 and CD7 surface expression but decreased CD13 and CD33 expression." (PMID 38643442, 2024). "A further strategy is to bridge allo-HSCT after achieving deep molecular remission with CD5/CD7 bispecific CAR-T therapy to reconstitute patients’ immune systems and subsequently achieve long-term leukemia-free survival." (PMID 35332132, 2022). "Naturally selected CD7 CAR-T cells efficiently killed CD7+ acute myeloid leukaemia cells and CD7+ primary blasts of R/R-AML patients in vitro and significantly inhibited leukaemia cell growth in a xenograft mouse model." (PMID 36517851, 2022). "3CAR or 7CAR cells were able to exert specific cytotoxicity against leukaemia lines with defined CD3 and/or CD7 expression as well as primary T-ALL cells." (PMID 34035409, 2021). "The development of leukemia was evaluated by regular flow cytometric analysis of human CD5 and CD7 T-ALL markers on peripheral blood." (PMID 33947863, 2021). "Here we investigated the genetic characteristics of CD7+/CD34+ and CD7+/CD34− cells from newly diagnosed human T-ALL and correlated it to the speed of leukemia development." (PMID 27191650, 2016). "We observed that CD7+/CD34+ or CD7+/CD34− T-ALL cells that promote leukemia within a short-time period are genetically similar, as well as xenograft-derived leukemia resulting from both cell fractions." (PMID 27191650, 2016). "In those cases, CD7+/CD34+/− cell fractions gave rise to genetically and phenotypically different leukemia in NSG mice." (PMID 27191650, 2016). "In our study, EKLF-positive AMLs were secondary leukemias with a low WBC count, CD15, CD11B and T-cell marker expression (such as CD7) in the blast cells, and high erythroblast percentage in the bone marrow." (PMID 22676581, 2012). "More recently, a CD7+CD1a− glucocorticoid resistant LIC population, capable of engrafting leukemia in NOD/SCID IL2Rγnull (NSG) mice, was identified in primarily adult T-ALL without an in vitro expansion step." (PMID 22768113, 2012). "The combination of HB2-SAP (anti-CD7) plus OKT10-SAP (anti-CD38) administered in 3 × 10 μg i.v. doses significantly increased survival time and the number of leukemia-free animals (60%)." (PMID 22069735, 2011). "Acute myeloid leukaemia patients with hypermethylation of any SFRP gene as a whole had higher frequency of CD19 (P=0.0004), CD7 (P=0.0144), and CD34 expression (P=0.012), but had lower frequency of CD14 expression (P=0.0395) on the leukaemia cells." (PMID 22095226, 2011). "In FCM, T-LGL leukemia cells revealed abnormal expression of CD5, CD7, and CD43 antigen, which corresponds to the findings of Lundell and colleagues." (PMID 18474096, 2008). "Among the patients, eight successfully achieved donor engraftment and experienced recovery of allogeneic hematopoiesis, though two of these patients later died from CD7-negative leukemia relapse and infection." (PMID 39864030, 2025). "Five patients in this group achieved complete remission (CR) and maintained minimal residual disease (MRD)-negative status; however, one eventually progressed to relapsed CD7-negative leukemia." (PMID 39864030, 2025).
leukemia (continued). "Further, K12 CAR-T cells effectively eliminated CD7-positive tumor cell lines as well as primary patient-derived CD7-positive T-ALL and AML in vitro and had prominent anti-leukemic activity in an intravenously (i.v.)injected leukemia xenograft mouse model, with complete remission in 60% of mice." (PMID 40589566, 2025). "With a median follow up of 15.1 months after CAR T-cell therapy, six patients remained in MRD-negative CR, two experienced a relapse of CD7-negative leukemia, and one patient died of septic shock at 3.7 months." (PMID 39199554, 2024). "There are four subtypes of T-ALL according to the European Group for the Immunological Classification of Leukemia (EGIL): pro-T EGIL T-I (iCD3+, CD7+), pre-T EGIL T-II (iCD3+, CD7+ and CD5/CD2+), cortical T EGIL T-III (iCD3+, Cd1a+, sCD3+/−), and mature-T EGIL T-IV (iCD3+, sCD3+, CD1a−)." (PMID 33810515, 2021). "While the occurrence of GPR56, CD53 and CD59a on leukemia cells is known, GPR56, CD53 and CD59a are highly expressed in the thymocytes of Lck-Lmo2 mice relative to wild type thymocytes and are also on the overt human tumors in addition to CD7." (PMID 30962539, 2019). "In the case of delayed T-ALL growth CD7+/CD34+ or CD7+/CD34− cells were either genetically diverse, the resulting xenograft leukemia arising from different but branched subclones present in the original sample, or similar, indicating decreased fitness to mouse micro-environment." (PMID 27191650, 2016). "Interestingly enough, these CD7+/CD34− derived xenografts developed slowly and were depleted in leukemia propagating activity in secondary transplants, outlining the more aggressive behaviour of the IKAROS deleted subclone." (PMID 27191650, 2016). "We killed moribund mice and detected their leukemia cells using flow cytometric analysis with cell suspensions from spleens and bone marrows using an APC- labeled anti-CD45 antibody and PE-labeled anti-CD7 antibody." (PMID 27083001, 2016). "In previous study, CD7 scFv-PE38 immunotoxin was only examinedin vitro with limited inhibition effect on primary leukemia cells and there was no in vivo examination tested." (PMID 27083001, 2016). "Many studies indicated that CD7 is expressed mainly on T-cell lymphoma and leukemia cell but absent from at least a small portion of normal T lymphocytes." (PMID 27083001, 2016). "In another leukemia subtype that is prone to early relapse, pediatric T cell acute lymphoblastic leukemia (T-ALL), serially transplantable LIC were found to be enriched in CD34+CD4− and CD34+CD7− fractions of newly diagnosed patient samples." (PMID 22768113, 2012). "Indeed we have found that 3/3 tested short term engrafting T-ALLs contain a predominant genetically defined clone endowed with xenograft leukemia development capacity that segregates with CD7+/CD34+ and CD7+/CD34− cell fractions, although the latter fraction was poorer in such function." (PMID 27191650, 2016). "Multiple subclones were found in 2/3 samples unequally distributed within the CD7+/CD34+ and CD7+/CD34− fractions, and their respective frequencies as well as oncogenic events seem to play roles in the specific abilities of CD34+/− cells to perpetrate leukemia in xenograft models." (PMID 27191650, 2016). "Thus differences in leukemia development abilities between CD7+/CD34+ and CD7+/CD34− cells in fast growing T-ALL do not rely on distinct early homing properties." (PMID 27191650, 2016). "The survival of severe combined immunodeficient (SCID) mice with disseminated NALM-6 leukaemia was significantly prolonged compared with sham-treated control animals by a course of therapy with BU12-SAPORIN but not with the irrelevant anti-CD7 immunotoxin HB2-SAPORIN." (PMID 8519647, 1995). "Only CD7+CD1a− leukemia cells successfully engrafted in NS122 recipients, while CD7− and CD7+CD1a+ cells showed no engraftment." (PMID 40805157, 2025).
leukemia (continued). "In our case, however, the leukemia cells was found negative for CD2, CD5 and CD7, making aberrant expression of AML relatively unlikely." (PMID 22356850, 2012). "CD5 and CD7 expression was variable (bright, dim, or negative) on all or part of the T-LGL leukemia cells, whereas in 3 cases lymphocytes showed an absence of both antigens." (PMID 18474096, 2008). "However, treatment of the CD7-negative cell lines RPMI8226 and H460 did not induce cleavage of PARP, demonstrating that PG001 induces apoptosis of CD7-positive leukemia-derived cell lines in an antigen-specific manner and is effective at low nanomolar concentrations." (PMID 27083001, 2016).
acute lymphoblastic leukemia (40 papers, 2012 to 2026). Leukemia with an acute onset, characterized by the presence of lymphoblasts in the bone marrow and the peripheral blood. "Here, we report two cases of confirmed relapsed/refractory (R/R) T-cell acute lymphoblastic leukemia (T-ALL) treated with autologous anti-CD7 CAR T cells infusion bridging to allo-HSCT." (PMID 41695358, 2026). "We explored the potential of Val-ILs targeted with an antibody against CD7 on T-cell acute lymphoblastic leukemia (T-ALL) cell lines." (PMID 38734740, 2024). "Most of the CD7-CAR T clinical trials have focused on T-acute lymphoblastic leukemia (ALL)/lymphoblastic lymphoma." (PMID 38711850, 2024). "Recently, CAR T cells targeting CD7 were used clinically to deeply purge relapsed T cell acute lymphoblastic leukemia." (PMID 37773046, 2023). "Several lymphatic diseases are associated with CD7-positive T cells or B cells, such as most cases of T cell acute lymphoblastic leukemia (T-ALL), some cases of acute myeloid leukemia (AML), and acute B lymphoblastic leukemia (B-ALL), as well as graft vs. host disease (GvHD)." (PMID 36430170, 2022). "Anti-CD7 CAR T have been tested in T cell acute lymphoblastic leukemia, with high response rates." (PMID 39528665, 2025). "CD7 is originally found in T cells of acute lymphoblastic leukemia." (PMID 30781701, 2019). "BEAM-201 (NCT05885464) is an allogeneic, CD7-directed CAR-T cell therapy developed for treating CD7-positive T-cell malignancies such as T-cell acute lymphoblastic leukemia (T-ALL)." (PMID 40968311, 2025). "CD7 is broadly expressed on T-cell acute lymphoblastic leukemia (T-ALL) cells as well as on normal T cells, leading to self-recognition and rapid elimination of CAR-Ts unless the antigen is ablated." (PMID 41281758, 2025). "Research has demonstrated that a significant proportion of T-cell acute lymphoblastic leukemia (T-ALL) and T-cell lymphomas overexpress CD7, rendering it a promising target for the treatment of these malignancies." (PMID 40463393, 2025). "While CD7 is expressed on T-cell acute lymphoblastic leukemia (T-ALL) blasts and most mature T-cell lymphomas, it is also expressed on most healthy T-cells, posing therapeutic challenges due to fratricide and T-cell aplasia." (PMID 39456582, 2024). "Donor-derived anti-CD7 CAR-T cells using endoplasmic reticulum retention have shown efficacy in patients with T-cell acute lymphoblastic leukemia (ALL)." (PMID 37095094, 2023). "Recently, in a pioneering first-in-human phase I trial (NCT04572308), naturally selected CD7 CAR-T-cell immunotherapy was applied to 20 patients with R/R T-cell acute lymphoblastic leukemia (T-ALL, n=14) and lymphoblastic lymphoma (T-LBL, n=6)." (PMID 37188182, 2023). "CD7 CAR T cells that have been genetically modified to prevent surface CD7 expression have demonstrated high rates of remission in patients with relapsed/refractory T-cell acute lymphoblastic leukemia (T-ALL)." (PMID 36172388, 2022). "CAR T cells transduced with an anti-CD7 intrabody applied in T-cell acute lymphoblastic leukemia (T-ALL) have been described." (PMID 35892709, 2022). "CD7-targeted chimeric antigen receptor-T (CAR-T) cell therapy has shown great promise in the treatment of relapsed/refractory T-cell acute lymphoblastic leukemia (T-ALL)." (PMID 39877371, 2025). "In T-cell acute lymphoblastic leukemia (T-ALL), frameshift or missense mutations in exons one to three of CD7 were associated with antigen-negative relapse following anti-CD7 CAR-T therapy." (PMID 41194129, 2025). "Specifically for lymphoblastic leukemia, the effect of PTL has been evaluated by Diamanti, who demonstrated that this compound can induce apoptosis in CD34+CD19− or CD34+CD7− ALL cells, preventing the engraftment capacity in NSG models." (PMID 39519261, 2024).
acute lymphoblastic leukemia (continued). "One recent research enrolled 60 patients with R/R T-cell acute lymphoblastic leukemia and lymphoblastic lymphoma (T-ALL/LBL), 58 of whom received autologous CD7 CAR-T cell therapy and 2 other patients received donor-derived CD7 CAR-T cell infusion." (PMID 39372412, 2024). "Current phase I/II clinical trials that engineer NK-92 cell lines with CARs to target CD19 (NCT02892695), CD33 (NCT02944162), CD7 (NCT02742727) on acute myeloid leukemia (AML) and acute lymphocytic leukemia (ALL) cells are ongoing." (PMID 39415291, 2024). "The resulting CAR T cells only eliminated CD7+ lymphoblastic leukemia T cells and not the CAR T cells also expressing CD7." (PMID 35892709, 2022). "Moreover, knocking out CD7 and TRAC in CAR T cells increased the efficacy in the treatment of T cell acute lymphoblastic leukemia (T ALL)." (PMID 33117331, 2020). "The underlying malignancies included T-acute lymphoblastic leukemia (ALL) (n = 1), diffuse large B cell lymphoma (DLBCL) (n = 4), and B-ALL (n = 3), and in accordance with it, CAR-T cells targeting CD7, CD19, and CD22 were infused, respectively." (PMID 39396970, 2024). "Studies have explored CD5-CAR-NK cells and CD7-CAR-NK cells for T-cell acute lymphoblastic leukemia (T-ALL) treatment and FLT3-CAR-NK cells in B-cell acute lymphoblastic leukemia (B-ALL)." (PMID 39007146, 2024). "For example, the UCART7 product for CD7+ acute lymphocytic leukemia (ALL) uses clustered regularly interspaced palindromic repeat (CRISPR)/Cas9 editing to simultaneously eliminate the endogenous T cell receptor alpha constant (TRAC) and CD7 genes, preventing GVHD and fratricide, respectively." (PMID 37654497, 2023). "For the immunophenotype analysis of M/NKPAL, Suzuki and Nakamura discovered that, among the main manifestations of M/NKPAL, CD7 is one of the most sensitive antigen indices to detect T cell acute lymphoblastic leukemia (T-ALL) but its specificity is not very strong." (PMID 27882252, 2016). "Researchers have found that CD7-negative T cells exist in the peripheral blood of healthy donors (0.72% to 19.5%) as well as patients with T-cell acute lymphoblastic leukemia (T-ALL) and B-cell acute lymphoblastic leukemia (B-ALL) (3% to 12.5%)." (PMID 37215124, 2023). "Donor-derived CD7-directed chimeric antigen receptor (CAR) T cells showed feasibility and early efficacy in patients with refractory or relapsed T-cell acute lymphoblastic leukemia (r/r T-ALL), in a previous phase I trial report, at a median follow-up of 6.3 months." (PMID 37020231, 2023).